TERT (telomerase reverse transcriptase)
Diseases named in the same sentence as TERT in open-access papers (continued):
Sharing a sentence is not in itself a finding about the gene and the disease.
hepatocellular carcinoma (continued). "Nucleotide changes in the TERT promoter are considered trunk mutations in liver carcinogenesis, being identified in a consistent fraction of dysplastic nodules and at increased frequency in hepatocellular carcinoma." (PMID 38033865, 2023). "TERT promoter mutations are so far the earliest recurrent genetic events in cirrhotic preneoplastic lesions and belong to the most frequent alterations in hepatocellular carcinoma." (PMID 32722302, 2020). "TERT promoter mutations have been identified in 6% of low-grade dysplastic nodules, 19% of high-grade dysplastic nodules, 61% of early hepatocellular carcinomas, and 42% of small and progressed HCC, correlating with step-wise development of hepatocarcinogenesis." (PMID 30073017, 2018). "In some tumour types, including hepatocellular carcinoma and follicular thyroid adenoma, TERT promoter mutations are early events in the neoplastic process and they might be useful to monitor tumour development from dysplastic lesions." (PMID 29562930, 2018). "To gain a broad understanding of the distribution of TERTp mutations in HCC, we conducted a comprehensive review of published data by searching PubMed using the keywords “TERT”, “promoter”, “mutations”, and “hepatocellular carcinoma”." (PMID 40243493, 2025). "Telomerase reverse transcriptase (TERT) mutations are the most frequent genetic alterations in hepatocellular carcinoma (HCC)." (PMID 33946181, 2021). "Telomerase reverse transcriptase (TERT) mutations are reportedly the most frequent somatic genetic alterations in hepatocellular carcinoma (HCC)." (PMID 33946181, 2021). "This study was designed to investigate the associations between TERT overexpression and the clinicopathologic factors of hepatocellular carcinoma (HCC)." (PMID 28947783, 2017). "Furthermore, we suggest the possibility of intratumoral genetic heterogeneity of TERT promoter mutations in hepatocellular carcinoma as indicated by the discordance in TERT promoter mutations between primary and corresponding recurrent hepatocellular carcinoma." (PMID 27661004, 2016). "The knockdown of ELF4 inhibits the expression of TERT and reduces the sphere-forming ability of hepatocellular carcinoma cells." (PMID 40083328, 2025). "The TERT promoter is altered in many cancers, including melanoma, liposarcoma, hepatocellular carcinoma, hepatocellular carcinoma and urothelial carcinoma." (PMID 38594465, 2024). "During mitosis, CDK1 phosphorylates TERT at threonine 249, and this posttranslational modification is essential for tumor formation in pancreatic cancer and hepatocellular carcinoma." (PMID 38278800, 2024). "Hepatocellular carcinoma (HCC) harboring TERT amplification has a poor prognosis, patients carrying TERT amplification in our study also exhibited a worse prognosis." (PMID 38970069, 2024). "The high expression of TERT can be used as an important prognostic index for intrahepatic metastasis of advanced hepatocellular carcinoma after radical resection." (PMID 36110223, 2022). "We and others have shown that TERT promoter mutations, causing hyperactivation of telomerase, are highly frequent in HPV-related cancers and HCV-related hepatocellular carcinoma." (PMID 36358677, 2022). "Two proteins encoded by HBV, namely HBx and surface (S) gene (preS2), have been shown to increase TERT expression and telomerase activity in hepatoma cells and in HCC cell lines, respectively." (PMID 36358677, 2022).
hepatocellular carcinoma (continued). "TERT, CSMD1, FRAS1 and ND5 are mutated in 28.6%, 5.7%, 5.2% and 5.3% of human hepatocellular carcinomas." (PMID 35557512, 2022). "These genes include the telomerase reverse transcriptase gene, TERT, CSMD1, a putative tumor suppressor that is frequently mutated in human hepatocellular carcinoma associated with HBV infection, FRAS1 and the mitochondrial encoded gene ND5." (PMID 35557512, 2022). "In this context, it is important to note that TERT expression is required for the proliferation of most cancer types including hepatocellular carcinomas, metastatic melanomas, and high-grade primary glioblastomas." (PMID 33397920, 2021). "ZnPP was the most potent MPP tested and down regulated TERT expression, arrested DNA synthesis, and promoted apoptosis in Huh7 hepatoma cells." (PMID 34747573, 2021). "Another intriguing mechanism that can activate TERT expression has been described in hepatocellular carcinoma, where a hepatitis B infection can result in integration of the virus genome near the TERT promotor." (PMID 34680452, 2021). "The TERT/SP1 interplay displays further complexity via evidence of co-activation roles on DNMT3B expression in hepatocellular carcinoma (HCC)." (PMID 33802026, 2021). "The amplified TERT gene was found in around 22% of hepatocellular carcinoma and shows a higher incidence in poorly differentiated hepatocellular carcinoma." (PMID 32722302, 2020). "Integration of the Hepatitis B virus into the host genome has been described in hepatocellular carcinoma, frequently in the TERT promoter region." (PMID 32722302, 2020). "Focal amplifications of 5p15.33 (TERT) were observed with a reduced overall survival, independently of other clinicopathological parameters in patients with hepatocellular carcinoma." (PMID 32722302, 2020). "Structural rearrangements in the TERT gene have been shown in several cancers like neuroblastoma, renal cell carcinoma, sarcoma and prostate carcinoma, and also in liver carcinoma." (PMID 32722302, 2020). "TERT promotermutations were significantly more frequent in hepatocellular carcinomas related to hepatitis C virus infection (5/6; 83.3%) compared to tumors of other etiologies (P = 0.001)." (PMID 27661004, 2016). "In conclusion, we identified TERT promoter and CTNNB1 mutations as the most frequent somatic genetic alterations observed in hepatocellular carcinoma, indicating its pivotal role in hepatocarcinogenesis." (PMID 27661004, 2016). "Emerging evidence (particularly for hepatocellular carcinoma) suggests that TERT could interact with BAP1 via the WNT/β-catenin signaling pathway, which is often activated in tumors with TERT overexpression." (PMID 39858033, 2025). "Notably, TERT is aberrantly upregulated in more than 80% of hepatocellular carcinoma (HCC) cases, making it an important target in liver cancer research." (PMID 40213897, 2025). "Indeed, the expression of HCV core protein in human hepatoma cells has been reported to increase TERT gene transcription, telomerase activity and localization of TERT in the nucleus." (PMID 36358677, 2022). "Moreover, a component of the telomerase complex, namely NHP2, has been found overexpressed along with TERT enzyme in HBV-related HCC as well as in HBx-transduced hepatoma cell lines." (PMID 36358677, 2022). "In contrast to that study, an analysis of 106 patient tissues (64 with HCC and 42 without liver disorders) and hepatocarcinoma cell lines revealed that the TERT promoter was methylated in normal liver but was hypomethylated in most of the hepatocellular carcinomas." (PMID 32722302, 2020). "Zhang et al38 found that TERT rs2242652 served as protective factors for the formation of hepatocellular carcinoma, which may be due to the reduced expression of TERT protein by this SNP." (PMID 31814184, 2020).
hepatocellular carcinoma (continued). "They found that TERT depletion in hepatocellular carcinoma cells (HCC) resulted in reduced DNMT3B transcription, and they proposed that TERT itself may cooperate with the transcription factor Sp1 to promote DNMT3B transcription." (PMID 32297856, 2020). "In conclusion, knockdown of NHP2 could inhibit the proliferation of hepatoma cells overexpressing HBx via inhibiting TERT expression." (PMID 33044946, 2020). "In contrast, other studies implicate that the occurrence of TERT mutations is more likely a secondary genetic event following the activation of an oncogenic signaling pathway, such as MAPK signaling in melanoma or Wnt signaling in hepatocellular carcinoma." (PMID 29463038, 2018). "Here, they identify an aggressive hepatocellular carcinoma subgroup exhibiting cyclin activation through various mechanisms and find this subgroup to display replication stress-induced structural rearrangements frequently activating TERT promoter." (PMID 30531861, 2018). "However, a recent report on four hepatocellular carcinoma cell lines described increased luciferase TERT promoter activity in the presence of the T349C SNP." (PMID 29100407, 2017). "In hepatocellular carcinoma (HCC), multiple mutations and dysregulated signaling pathways, including WNT, MAPK, mTOR, TGF-β, STAT, and TERT, drive tumor initiation and progression." (PMID 40563418, 2025). "In our previous study, we had confirmed that methylation status of TERT was strongly correlated with its expression in hepatocellular carcinoma (HCC)." (PMID 36275754, 2022). "Hepatitis B virus X protein (HBx) is highly expressed in HBV-infected hepatocellular carcinoma (HCC) and upregulates transcriptional activation of telomerase reverse transcriptase (TERT)." (PMID 33044946, 2020). "A2/B1 and TERT co-purify both in vitro and in hepatocellular carcinoma (HCC) tissue samples, and A2/B1 depletion impairs telomerase activity in HCC HUH7 cells." (PMID 32599885, 2020). "Moreover, the combination of the expression of SP1, NACO3, and TERT may serve as a survival predictor in hepatocellular carcinoma." (PMID 33239622, 2020). "However, analyses of TERT promoter and CTNNB1 mutations in hepatocellular carcinoma tumor samples have not been performed in the Korean population, where hepatitis B virus-related hepatocellular carcinoma is prevalent." (PMID 27661004, 2016). "Telomerase reactivation during hepatocarcinogenesis is recurrently caused by two point mutations occurring most frequently at the nucleotide −124 (95%) and occasionally at the nucleotide −146 (<5%) upstream of the TERT translational start site in hepatocellular carcinoma (HCC)." (PMID 34359670, 2021). "Via regulating the telomerase reverse transcriptase (TERT) signaling, NCOA3 promoted cell viability and colony formation in hepatocellular carcinoma cells, and high expression of NCOA3 had worse prognosis." (PMID 34593007, 2021). "We have recently found that SIRT1 expression is highly elevated in hepatocellular carcinoma, and the depletion of SIRT1 leads to substantial reduction in TERT mRNA and protein expression." (PMID 24416313, 2014).
hepatocellular carcinoma (continued). "To confirm whether HBx could directly affect TERT and NHP2 expression, we constructed two vectors to overexpress HBx in PLC/PRF5 hepatoma cells." (PMID 33044946, 2020). "It is not clear at this time why our hepatoma cell lines, either infected or uninfected, contained most of the cellular TERT in the cytoplasm." (PMID 28056029, 2017). "Like all human hepatoma cell lines, Huh-7.5 cells produce some TERT regardless of infection, but the amount was increased over 100% (by density analysis, not shown) by 2 days after HCV infection." (PMID 28056029, 2017). "However, no reports are available on the impact of rs2853669 on TERT expression in hepatocellular carcinoma (HCC) and its association with patient survival." (PMID 26575952, 2016). "TERT promoter and CTNNB1 mutations were only observed in hepatocellular carcinomas but not in precursor lesions." (PMID 27661004, 2016). "Genetic alterations of TERT and CTNNB1 have been documented in hepatocellular carcinoma." (PMID 27661004, 2016). "In this study, we aimed to assess in hepatocellular carcinoma (HCC) the cellular and extracellular expression of TERRA, the telomerase RNA subunit (TERC) and the telomerase catalytic subunit (TERT)." (PMID 35682861, 2022). "Recurrent somatic mutations in the promoter region of telomerase reverse transcriptase (TERT) gene and in the exon 3 of CTNNB1 gene have been recognized as common events in hepatocellular carcinoma (HCC) with variable frequencies depending on etiology and geographical region." (PMID 27276713, 2016).
papillary thyroid carcinoma (93 papers, 2016 to 2026). "Telomerase reverse transcriptase promoter mutations (TERT) are known prognostic factors associated with poor outcomes in differentiated thyroid carcinoma (DTC)." (PMID 41604294, 2026). "The authors reported that TERT promoter DNA methylation upregulates TERT expression and associates with poor clinical outcomes of papillary thyroid cancer (PTC), thus holding the potential to be a valuable prognostic marker for PTC risk stratification." (PMID 41375001, 2025). "In a study that included 332 cases of papillary thyroid cancer, the presence of the TERT mutation was identified as an independent indicator of persistent disease in well-differentiated thyroid cancer." (PMID 39744583, 2025). "Independently, TERT promoter mutation is linked with the anaplastic transformation of papillary carcinoma." (PMID 40271195, 2025). "The C216T mutation in the TERT promoter (TERTp) is a rarely reported genetic alteration in papillary thyroid carcinoma (PTC)." (PMID 39934880, 2025). "Together, this evidence indicates that coexisting BRAF V600E and TERT promoter mutations synergistically drive tumor progression and enhance malignant behavior in papillary thyroid carcinoma." (PMID 40469184, 2025). "Our results further confirm the prognostic value of TERT mutations in the overall population of papillary thyroid cancer patients, demonstrating a nearly 1.9-fold increase in the risk of mortality (HR = 1.90, 95% CI: 1.17–4.77)." (PMID 40149275, 2025). "In a meta-analysis of TERT promoter mutations in papillary thyroid carcinoma, it was found that they are closely associated with aggressive clinicopathological factors and poorer prognosis." (PMID 40307280, 2025). "In conclusion, TERT mutations play a crucial role in the pathogenesis of papillary thyroid cancer, influencing tumor aggressiveness, recurrence, and patient prognosis." (PMID 39744583, 2025). "BRAF V600E and telomerase reverse transcriptase (TERT) promoter mutations synergistically drive recurrence and mortality in papillary thyroid cancer." (PMID 40988283, 2025). "One high-grade differentiated thyroid carcinoma with co-existing G469A and TERT mutations was found." (PMID 40075589, 2025). "Our prior study also demonstrated that BRAFV600E coexisting with TERT promoter mutations contributes to adverse clinical outcomes in radioiodine-refractory differentiated thyroid cancer." (PMID 40895628, 2025). "The predictive value of allele frequency (AF) of BRAF V600E and TERT mutations in papillary thyroid carcinoma (PTC) remains controversial." (PMID 38607456, 2024). "Studies on small papillary carcinomas (papillary thyroid microcarcinomas) found hotspot TERT promotor mutations in 0 to 8.7% of tumors." (PMID 38616265, 2024). "Our study was also in keeping with other studies in the literature that showed poor clinicopathological outcomes for papillary thyroid cancer with concurrent TERT and BRAF V600E mutations." (PMID 36672362, 2023). "The prevalence of TERT promoter mutations in papillary thyroid cancer is estimated to be between 5% and 25%, varying among subtypes." (PMID 36672362, 2023). "In conventional papillary thyroid carcinoma, TERT promoter mutations are often associated with subtypes showing aggressive clinical behavior, including the tall cell and hobnail subtypes." (PMID 36984536, 2023). "As loss of 5-hydroxymethylcytosine (5hmC) has been associated with TERT promoter mutations in papillary thyroid carcinoma, this study sought to analyze the levels of 5hmC in a cohort of follicular thyroid tumors with available TERT data." (PMID 37486076, 2023). "Papillary carcinomas with TERT promoter mutations are usually characterized as being mainly found in older patients, having larger tumor sizes, frequent lymph node and distant metastases, advanced TNM stages, and more recurrences." (PMID 37544981, 2023).